CAMK4 (calcium/calmodulin dependent protein kinase IV)
Diseases named in the same sentence as CAMK4 in open-access papers (continued):
Sharing a sentence is not in itself a finding about the gene and the disease.
Huntington disease (1 paper, 2022). Huntington disease (HD) is a rare neurodegenerative disorder of the central nervous system characterized by unwanted choreatic movements, behavioral and psychiatric disturbances and dementia. "Three of these were downregulated in Huntington’s disease compared with WT mice under SH conditions (MAST3, PRKCB and CAMK4) and could therefore be responsible for changes in the phosphoproteome observed between these two groups." (PMID 36523271, 2022).
Hyperglycemia (1 paper, 2023). An increased concentration of glucose in the blood. "While suppressed glycolysis were found in placenta of pregnant women with hyperglycemia, suggesting that CAMK4 overexpression may be beneficial for glycometabolism regulation although its effectiveness and safety needed to be confirmed in experimental GDM animals." (PMID 37386367, 2023). "Therefore, it remains further experiments to confirm whether the alterations of CAMK4/NUR77 expression and autophagy are associated with IR or hyperglycemia or hyperinsulinemia in the future." (PMID 37386367, 2023).
kidney damage (1 paper, 2024). "Indeed, CaMK4 is involved in the dysregulation of several subsets of T cells, including Tfh, Treg8,9, and Th17 cells, but also in the promotion of kidney damage through its expression in podocytes." (PMID 38287012, 2024).
male infertility (1 paper, 2018). The inability of the male to effect fertilization of an ovum after a specified period of unprotected intercourse. "Disrupted CAMK4 expression may be associated with human male infertility." (PMID 29416565, 2018). "Previous studies suggested that disruptions of CAMK4 located on chromosome 5q22.1, SPINK13 located on chromosome5q32 and the testis-specific serine/threonine kinase (TSSK1B) gene mapped to chromosome 5q22.2 were associated with loss of sperm function and human male infertility." (PMID 29416565, 2018).
melanoma (1 paper, 2025). A malignant, usually aggressive tumor composed of atypical, neoplastic melanocytes. "We subsequently also verified SLC27A5 and CAMK4, in which we identified mutation clusters of interest in melanoma." (PMID 40359938, 2025).
osteoporosis (1 paper, 2023). A condition of reduced bone mass, with decreased cortical thickness and a decrease in the number and size of the trabeculae of cancellous bone (but normal chemical composition), resulting in increased fracture incidence. "Five genes remained after the LASSO feature selection, and the formula for the osteoporosis risk score (ORS) was established as follows: ORS = 33.991 - 2.272 * ABCD2 - 6.201* RORA + 2.237 * ITK - 1.100 * CAMK4 + 0.466 * RASGRP1." (PMID 37051201, 2023).
periapical periodontitis (1 paper, 2025). Inflammation of the periapical tissue. "This study unveils that hypoxia exposure, acting as a critical environmental risk factor, functions as a 'synergistic amplifier' to enhance pathological osteoclastic responses in periapical periodontitis through the HIF-2α-CAMK4 regulatory axis." (PMID 41467319, 2025).
primary hypertension (1 paper, 2025). "CaMK4 mediates ER-related calcium overload, while CACNA1C is linked to primary hypertension." (PMID 41019540, 2025).
renal cystic disease (1 paper, 2022). "Additional studies are needed to delineate the interactions between CaMK4, GSK3β, and mTOR in the setting of renal cystic disease." (PMID 36002021, 2022).
scrapie (1 paper, 2014). A fatal disease of the nervous system in sheep and goats, characterized by pruritus, debility, and locomotor incoordination. "Calcineurin regulates the activity of CaMK4 and CREB, and elevated calcineurin activity was observed in scrapie-infected mice at clinical stages of disease." (PMID 25183307, 2014).
tauopathy (1 paper, 2024). Neurodegenerative disorders involving deposition of abnormal tau protein isoforms (tau proteins) in neurons and glial cells in the brain. "Tauopathy and the development of amyloid plaques are encouraged when the CAMK4 gene, which controls synaptic activities in neuronal cells, is inhibited by microRNAs." (PMID 39200803, 2024).
cancer (12 papers, 2019 to 2025). A tumor composed of atypical neoplastic, often pleomorphic cells that invade other tissues. "Molecular docking studies indicate that vanillin has a strong binding affinity for calcium/calmodulin-dependent protein kinase IV (CaMKIV), an enzyme implicated in the progression of cancer and neurodegenerative diseases." (PMID 41590042, 2025). "In addition, CAMK4, which is a target protein for neurological diseases and cancer, has a desirable drug design value, suggesting that CAMK4 may be a target for drugs with better potential for anti-hepatocarcinoma." (PMID 31624237, 2019). "Carotenoids can decrease the calcium/calmodulin-dependent protein kinase IV (CAMKIV) enzyme by binding with the active site of CAMKIV; that form allows the cancer cell apoptosis." (PMID 34336128, 2021).
tumor (10 papers, 2019 to 2025). "Eight cases out of 48 clinical samples were randomly chosen for detection, and we found that CAMK4 was highly expressed in normal tissues adjacent, whereas the expression level in tumor tissues was significantly decreased." (PMID 31624237, 2019). "To further demonstrate the antitumor effects of CAMK4, we performed studies by establishing the CAMK4 overexpressing tumor-bearing mice model." (PMID 31624237, 2019). "Our data observed that for HepG2 and BEL-7402 cells, the tumor weight in the CAMK4 group was lighter than that in the control group and NC group, whereas the tumor volume in the CAMK4 group was smaller than that in the control group and NC group." (PMID 31624237, 2019). "As a direct target gene of miR-129-5p, CAMK4 could inhibit tumor by inhibiting the activation of MAPK signaling pathway." (PMID 31624237, 2019). "CAMK4, which is a direct target gene of miR-129–5p, could inhibit tumor by inhibiting the activation of MAPK signaling pathway." (PMID 31624237, 2019). "In addition, the immunohistochemistry experiment results showed that the tumor tissues in the CAMK4 group were significantly upregulated." (PMID 31624237, 2019). "Similarly, the C4 subgroup was identified in the tumor tissues of the validation cohort, exhibiting a high similarity to CD4_THEMIS cells and expressing high levels of CBLB, THEMIS, and CAMK4." (PMID 38948071, 2024). "It is also known as protein kinase B (PKB) play an important role in angiogenesis in pathological condition and tumor growth via different Ser/Thr kinase family members like liver kinase B1 (LKB1), calcium/calmodulin-dependent protein kinase IV (CAMKIV), and sulfatase (SULF2)." (PMID 34754365, 2021).
infection (3 papers, 2020 to 2026). The state of being infected such as from the introduction of a foreign agent such as serum, vaccine, antigenic substance or organism. "The function of CAMK4 was investigated by transfection of overexpression plasmid in HTR-8/SVneo cells and infection of lentivirus loaded with CAMK4 encoding sequence in primary trophoblast cells." (PMID 37386367, 2023).
neurological diseases (3 papers, 2018 to 2022). "Our findings highlight the importance of CAMK4 in human neurodevelopment, provide a foundation for future clinical research of CAMK4, and suggest the CaMKIV signaling pathway as a potential drug target in neurological disease." (PMID 30262571, 2018). "Some studies have revealed the effect of CAMK4 on regulating NOS in neurological diseases, but the mechanism of its reproductive regulation remains unclear." (PMID 35741727, 2022).
kidney disease (1 paper, 2021). "In addition, we demonstrate that increased expression of CaMK4 in biopsy specimens and in urine podocytes from people with LN is linked to active kidney disease." (PMID 33784256, 2021).
CAMK4 also shares sentences with these, for which no sentence is quoted: Stroke (7 papers); cardiac hypertrophy (4); cardiovascular disease (3); Cerebral ischemia (3); endothelial dysfunction (3); myocardial infarction (3); neurodegenerative disease (3); prostate carcinoma (3); acute kidney injury (2); Ataxia (2); COVID-19 (2); diabetic retinopathy (2); hypothyroidism (2); ischemia (2); memory impairment (2); nicotine addiction (2); schizophrenia (2); type 2 diabetes (2); acute leukemia (1); acute lung injury (1); Allergy (1); anxiety disorder (1); Arrhythmia (1); breast carcinoma (1); Cerebellar atrophy (1); cocaine dependence (1); cognitive disorder (1); colorectal carcinoma (1); congenital hypothyroidism (1); dermatosis (1).
A further 30 diseases each share a sentence with CAMK4 in 1 paper.